ZNF143 (zinc finger protein 143)
Diseases named in the same sentence as ZNF143 in open-access papers (continued):
Sharing a sentence is not in itself a finding about the gene and the disease.
cancer (continued). "Based on this finding, we might hypothesize that ZNF143’s potential to change the main cancer signaling pathways may originate from CDKN1B, PIAS4, CTBP2, and ABCC1." (PMID 36675976, 2022). "Here, CDKN1B, PIAS4, CTBP2, and ABCC1 could be the potential source for ZNF143 to alter the major cancer signaling pathways." (PMID 36675976, 2022). "Based on this result, we could conclude that CDKN1B, PIAS4, CTBP2, and ABCC1 could be the potential source for ZNF143 (because these genes link more biological functions) to alter the major cancer signaling pathways." (PMID 36675976, 2022). "Studies have revealed that ZNF143 is involved in various cellular and biological processes, including cell growth, cell proliferation, cell cycle regulation, cancer development, DNA repair, embryonic development, hematopoietic stem and progenitor cell identity, and genetic disorders." (PMID 35780101, 2022). "Furthermore, ZNF143 was among several other ligand-independent cofactors enriched in cancer cell lines derived from ovarian and uterus tissues." (PMID 33540646, 2021). "Within the tumour microenvironment, IL‐8 signalling is initiated by binding of its G‐protein‐coupled receptors CXCR1/2.33, 39 To examine whether ZNF143 expression affects on IL‐8 signalling in cancer cells, we examined the mRNA expression of CXCR1/2." (PMID 30933430, 2019). "The target genes of ZNF143 were shown to be fundamental for cancer progression." (PMID 30885238, 2019). "Since ZNF143 controls both DNA replication and the expressions of cell cycle regulatory molecules, it may potentially find application in cancer diagnostics and treatment." (PMID 30885238, 2019). "From pathway analyses, we obtained new insights into how ZNF143 affected cancer cell function." (PMID 30935019, 2019). "We believe that ZNF143 is a promising molecular target to overcome cancers." (PMID 24213117, 2011). "Deregulation of the cell cycle-dependent fluctuation in ZNF143 expression also might prevent the cancer proliferation even if cancer cells maintain strong expression of ZNF143." (PMID 24213117, 2011). "Thus, our results confirm that FBXO9 mediates the cancer-promoting effect of ZNF143 in HCC." (PMID 35847937, 2022). "Moreover, ZNF143 is implicated in the regulation of E-cadherin expression through ZEB1, and the loss of E-cadherin by the ZNF143-ZEB1-linked cascade was shown to be related to cancer cell motility." (PMID 30885238, 2019). "Therefore, abnormal expression of ZNF143 is related to cancer cell survival, proliferation, differentiation, migration, and invasion, suggesting that new small molecules can be designed by targeting ZNF143 as it may be a good potential biomarker and therapeutic target for related cancers." (PMID 32318100, 2020). "Interestingly, some of the transcription factors identified, such as ZNF143 in K562 and GATA3 in MCF-7, play important roles in the relevant cancer types." (PMID 34399797, 2021).
tumor (11 papers, 2017 to 2023). "The abnormal expression of ZNF143 is associated with tumor progression, as reported in our previous study and other studies." (PMID 35847937, 2022). "Particularly for P4, the shared mutations included several important tumor metastasis–related and drug-resistance genes, such as ZNF143, MUC16, NUMA1, ADAMTS2, and MOV10." (PMID 34616428, 2021). "ZNF143 positively regulates tumor growth through transcriptional regulation of DNA replication and cell-cycle-associated genes (such as CDC6, PLK1, and MCMs) in multiple solid tumors, including in LCs." (PMID 34616428, 2021). "The role of ZNF143 in the proliferation of GC cells in vivo was examined using tumor xenograft assay." (PMID 32076462, 2020). "Further, ZNF143 overexpression suppressed the apoptosis of GC cells in vitro and promoted tumor growth in nude mice in vivo." (PMID 32076462, 2020). "The transplanted tumor weight and volume were higher in the ZNF143-overexpressed group than in the ZNF143-knockdown group in vivo was examined using tumor xenograft assay." (PMID 32076462, 2020). "CD20641 and IL‐642 were shown to be expressed more in cells with CM‐cells with less ZNF143 than in cells with CM‐control cells, implying factors from ZNF143 knockdown cells for pro‐tumoural tumour microenvironments." (PMID 30933430, 2019). "Whereas, overexpression of ZNF143 reversed the miR-590-3p-mediated tumor-suppressive effects through elevating ASAP3 and MYB expression." (PMID 31186064, 2019). "Regardless of growing system, ZNF143 expression showed to affect IL‐8 expression, suggesting a role of ZNF143 for cytokine regulation for tumour progression." (PMID 30933430, 2019). "Multiple reports have proven that ZNF143 plays a role in cancer drug resistance and the DNA repair of tumor cells." (PMID 31186064, 2019). "The disordered expression of ZNF143 is closely related to the malignant progression of tumours." (PMID 37423952, 2023). "ZNF143, as a tumor oncogene, promoted the proliferation of GC cells both in vitro and in vivo, indicating that ZNF143 might function as a novel target for GC therapy.in vitro." (PMID 32076462, 2020). "In this study, we have been suggested that ZNF143 expression may be important in the tumour microenvironment by regulating secreted molecules, such as cytokines, which may communicate with other cells." (PMID 30933430, 2019). "In addition to IL‐8, we also found that expression of the chemokines MIF and IL‐10, which have been shown to mediate tumour‐promoting crosstalk between tumours and the tumour microenvironment, was increased following ZNF143 knockdown." (PMID 30933430, 2019). "However, it remains unclear how ZNF143 expression is related to tumour progression within the tumour microenvironment." (PMID 30933430, 2019). "Mechanistically, as a direct upstream transcription factor, FBXO9 is regulated by zinc finger protein 143 (ZNF143) and accelerates tumor growth and metastasis by targeting the F-box and WD repeat domain containing 7 (FBXW7) for ubiquitination and degradation." (PMID 35847937, 2022). "It is noteworthy that activation of the MAPK/ERK and PI3K/Akt pathways is an important step required for EMT process induced by various tumor-related factors including TGF-β, TACC3, EGF, BMP7, ZNF143, and CXCR4 26-31." (PMID 31417642, 2019). "Three genes (ZNF143, ALDOA and LEPROTL1) were among the top 30% of genes that are univariately informative of the proximity-to-tumour label." (PMID 29093438, 2017).
infection (2 papers, 2020 to 2025). The state of being infected such as from the introduction of a foreign agent such as serum, vaccine, antigenic substance or organism. "The expression of ZNF143 in BGC823 cells was detected once again to verify the infection efficiency." (PMID 32076462, 2020). "Other TFs in the network (e.g., PPARG, TFAP2A, ZNF143) may modulate expression for homeostasis or fine-tune the response depending on infection stage." (PMID 41408150, 2025).
ZNF143 also shares sentences with these, for which no sentence is quoted: myeloid leukaemia (2 papers); autism spectrum disorder (1); Cranial meningocele (1); Endothelial Corneal Dystrophy (1); lymph node metastasis (1); myeloid neoplasm (1); neuroblastoma (1); partial epilepsy (1); prostate tumors (1); psoriasis (1); serous borderline ovarian tumors (1); trigonocephaly (1); type 2 diabetes mellitus (1).